C16orf90 (chromosome 16 open reading frame 90)
Synonyms: LOC646174
Tractability: No criterion of Open Targets' tractability assessment is met for any kind of drug.
Gene: Protein-coding gene on chromosome 16 (3,493,484 to 3,495,489, reverse strand). Ensembl gene ENSG00000215131.
Genetic constraint (gnomAD): Loss-of-function variants: 17 observed, 15.92 expected, observed/expected ratio (o/e) 1.07, 90% interval 0.73 to 1.59. The upper end of that interval is the gene's LOEUF score, 1.59, which puts it in group 6 of 6, group 1 being the genes least tolerant of losing a copy. Missense variants: 255 observed, 225.47 expected, observed/expected ratio (o/e) 1.13, 90% interval 1.02 to 1.25. Synonymous variants: 108 observed, 90.83 expected, observed/expected ratio (o/e) 1.19, 90% interval 1.02 to 1.39.
Homologues: Orthologues: chimpanzee C16H16orf90 (99% identical), macaque C20H16orf90 (96% identical), dog C16orf90 (77% identical), pig C16orf90 (77% identical), rat C10h16orf90 (76% identical), mouse 1700037C18Rik (72% identical), rabbit C16orf90 (71% identical).
Diseases named in the same sentence as C16orf90 in open-access papers:
C16orf90 is named in the same sentence as 3 diseases in open-access papers, as found by Europe PMC text mining. Sharing a sentence is not in itself a finding about the gene and the disease.
C16orf90 shares sentences with these, for which no sentence is quoted: diabetes (1 paper); metastatic melanoma (1); metastatic tumors (1).